PPARG (peroxisome proliferator activated receptor gamma)
Diseases named in the same sentence as PPARG in open-access papers (continued):
Sharing a sentence is not in itself a finding about the gene and the disease.
colon carcinoma (continued). "The induction of differentiation by activation of PPARγ may represent a promising novel therapeutic approach for cancer as already demonstrated for liposarcoma and in xenograft models of prostate and colon cancer." (PMID 22685453, 2012). "PPARγ activation by Fas could explain the link between high fat diets and colon cancer." (PMID 20182546, 2010). "PPARγ expression is reduced in ulcerative colitis and acromegaly, two conditions thatpredispose to colon cancer; and one might extrapolate from data with hemizygousknockout mice to postulate that areduction in PPARγ expression increases the likelihood oftransformation in the human colon." (PMID 18615192, 2008). "Thus, it seems thatcapsaicin-induced apoptotic cell death in colon cancer cells is associated withthe PPARγ pathway without the involvement of thevanilloid receptor." (PMID 18615184, 2008). "Although these studies suggest that PPARγ functions as a tumor suppressor factorand its activation might be beneficialfor patients with tumors, PPARγ agonists have been shown also toincrease the frequency of colon tumors and to promote edema." (PMID 18725983, 2008). "Indeed, PPARγ agonists have been shown to suppress monocyte elaboration of inflammatory cytokines and to inhibit IL-1β-induced expression of IL-8 in colon cancer cell lines." (PMID 12454768, 2002). "For example, the PPARγ agonist 15-d-PGJ2 suppresses tumor cytokine expression by inhibiting the NF-kB pathway in Caco-2 and HT-29 colon cancer cell lines." (PMID 39875357, 2025). "Based on mouse models constructed from the colon cancer cell line CT26 and breast cancer cell line 4T1, the PPARγ agonist rosiglitazone was found to remodel the tumor vasculature system and limit tumor-associated macrophage (TAM) infiltration." (PMID 39875357, 2025). "BER has previously been demonstrated to decrease lipid accumulation in porcine oocytes, colon cancer cells, and mouse liver tissue by suppressing the expression of genes that drive lipid buildup, such as SCAP, SREBP-1, PPARG, SCD1, and FASN." (PMID 37237857, 2023). "It has been documented that after addition of EGFR, MDM2 can bind to PPARγ and regulate the ubiquitination of PPARγ protein in colon cancer, and that MDM2 silencing can increase the level of PPARγ, which is further verified in bladder cancer." (PMID 36230661, 2022). "The present study aimed to investigate the effect of the PPARγ agonist pioglitazone on tumor metastasis and liver injury following IRI in a mouse model of colon cancer." (PMID 33122687, 2020). "We investigated PPARγ and PSF mRNA and protein expression in 4 human colon cancer cell lines, HT-29, DLD-1, Caco-2, and LOVO." (PMID 23516550, 2013). "Accordingly, activation of PPARγ with ROSI, in combination with 5-FU treatment, has been evaluated in HCC and colon cancer." (PMID 22966225, 2012). "CDDO has been shown to induce transactivation and PPARγ interaction with multiple coactivators including SRC-1, SRC-2, SRC-3, TRAP 220, CARM-1, and PGC-1 in colon cancer cells." (PMID 22685453, 2012). "For example, two PPARγ agonists, troglitazone and rosigliatzone, have been reported to promote gastrointestinal tumorigenesis in C57BL/6J APCMin/+ mice, raising the serious concerns about the possibility that individuals who are on TZDs for T2DM might be at risk for colon cancer." (PMID 19884989, 2009). "Biallelic knockout of PPARγ in colonic epithelial cells resulted in increased tumor incidence and tumor size in APC+/Min mice, and Pioglitazone suppressed colon tumor growth in APC+/Min mice in a dose-dependent manner." (PMID 19884989, 2009). "Combiningthe PPARγ agonist, pioglitazone, with the PPARγ antagonists T0070907 or GW9662 actually increased growthinhibition in a colon cancer cell line compared to each agent alone." (PMID 18615184, 2008). "PPARγ agonists induce apoptosis by inductionof PTEN expression in pancreatic, breast, and colon cancer cells and inhibition of NFκB and Bcl-2 expression in colon cancercells." (PMID 18551185, 2008).
colon carcinoma (continued). "The activation of PPARγ/RXR heterodimer by their respective ligands synergistically inhibits cell growth, while inducing apoptosis in human colon cancer cells when the phosphorylation of RXRα was inhibited." (PMID 18528526, 2008). "Furthermore, Takano and colleagues found that the PPARγ agonist pioglitazone down-regulated COX-2 and cyclin D1 and inhibited colon cancer proliferation and liver metastasis." (PMID 39875357, 2025). "Furthermore, in mice with hemizygous PPARG knockdown, an increased incidence of CRC was observed after inducement of colon cancer by Azoxymethane treatment." (PMID 38378472, 2024). "In colon cancer, the absence of PPARα and PPARβ/δ expression promotes cancer growth, and PPARγ suppresses tumorigenesis through the regulation of and interaction with β-catenin." (PMID 36221049, 2022). "However the activation of PPARγ can lead to increased ABCA1 gene transcription in macrophages and ABCA1 has shown to have anticancer activity in colon cancer cells." (PMID 32982759, 2020). "The stratified analysis revealed that the PPARG rs3856806 C>T polymorphism also increased the risk of CRC, especially in male, ≥61 years old, never smoking, never drinking, BMI ≥ 24 kg/m2, colon cancer and rectum cancer subgroups." (PMID 30838172, 2019). "However, it has also been reported that PPARγ-β-catenin interaction seems to increase the stability of the PPARγ protein and enhance PPARγ activity in APCMin mice and in SW480 human colon cancer cells." (PMID 31546785, 2019). "High enrichment of fat cell differentiation term in the SM-treated samples can be explained by the effect of SM on PPARγ, playing a key role in adipocyte differentiation – previously, it was found that CDODA-Me had agonist activity on PPARγ (1-5 μM; SW480 colon cancer cells (20–22 h))." (PMID 31523389, 2019). "In this study, we examined the interrelationship of β-catenin, COX-2, PPARγ, and IL-17 in patients with sporadic colon cancer compared to subjects without cancer." (PMID 30186819, 2018). "Previous studies showed that PPARγ can suppress beta-catenin levels and colon carcinogenesis but only before damage to the APC/beta-catenin pathway, suggesting a potentially important use for PPARγ ligands as chemopreventive agents in colon cancer." (PMID 29221176, 2017). "Also, activation of PPARγ correlates with an increase in CAV1 mRNA in breast and colon cancer cells, and RANKL up-regulates CAV1 during osteoclastogenesis." (PMID 29340103, 2017). "However, in the case of colon cancers with known deletions in the APC (adenomatous polyposis coli) tumor suppressor gene, PPARγ agonists appear to promote tumor growth, and increase the number of colon polyps, possibly by increasing the uptake of dietary fat." (PMID 24672773, 2014). "PPARγ upregulates PTEN expression, which is involved in the inhibition of cell growth and the induction of cell apoptosis in various cancer cells, including hepatocellular carcinoma, colon cancer, and non-small-cell lung cancer cells (NSCLC)." (PMID 24757676, 2014). "The antiproliferative and apoptotic effects of pioglitazone in the human colon cancer cells were not completely deregulated by PPARγ blockade with GW9662." (PMID 25360175, 2014). "PPARγ blockage did not neutralize the effect of pioglitazone on PPARγ mRNA expression in all three colon cancer cell lines (HT-29, Δ0.42; SW-480, Δ0.48; and SW-620, 0.27; P<0.05)." (PMID 25360175, 2014). "Similarly, the addition of 2.5 μM of the PPARγ blocker, GW9662, also resulted in significant caspase 3/7 activation (P<0.05) in all three colon cancer cell lines." (PMID 25360175, 2014). "Although PPARγ agonists inhibit colorectal carcinogenesis inxenograft models and in the azoxymethane (AOM)-induced colon cancer model, these drugs are reported to have bothtumor-promoting and tumor-inhibiting effects in a mouse model for familialadenomatous polyposis, the ApcMin/+ mouse." (PMID 18551185, 2008).
colon carcinoma (continued). "Some of these effectsare PPARγ-dependent, but the potential role of othertargets is suggested by the similar effects of BADGE on a PPARγ+ colon cancer line and a PPARγ-negative T-lymphoma line." (PMID 18779871, 2008). "In colon cancer cells, capsaicininduced apoptotic cell death; this effect was completely blocked by bisphenol Adiglycidyl ether, a specific PPARγ antagonist, but not by capsazepine, aspecific antagonist for vanilloid receptor." (PMID 18615184, 2008). "We confirmed antimetastaticeffect of PPARγ by CLA in gastric and colon cancer cells." (PMID 18551182, 2008). "“In vivo” PPARγ and α were evaluated in colon cancer specimens and adjacent nonneoplastic colonic mucosa." (PMID 17389773, 2007). "In human colon cancer samples, a significant correlation between PPARγ and the expression of pRb, cyclin D1, p16, and p21 was found; however, surprisingly, PPARγ expression did not correlate with the stage, grade of differentiation, metastasis, tumor proliferative capacity, or patient survival." (PMID 35954274, 2022). "Various studies have shown that PPARγ activation inhibits cell growth and induces differentiation and apoptosis in colon cancer cells; embelin was able to reduce cell proliferation and induce apoptosis both in HCT116 and HT-29 colon cancer cells, by increasing PPARγ receptor expression." (PMID 32283655, 2020). "The authors found that the compounds of LWDHW may play an important role in esophagitis and colon cancer by regulating the expression of C-C chemokine receptor 2 (CCR2), estrogen receptor 1 (ESR1), peroxisome proliferator-activated receptor gamma (PPARG), and retinoic acid receptor alpha (RARA)." (PMID 30846939, 2019). "Our findings suggested that the PPARG rs3856806 C>T polymorphism is associated with an increased risk of CRC, especially in male, ≥ 61 years old, never smoking, never drinking, BMI ≥24 kg/m2, colon cancer, and rectum cancer subgroups." (PMID 30838172, 2019). "In colon cancer cells, activation of PPARγ by troglitazone treatment inhibits growth and metastasis through differentiation-promoting effects, such as the marked increase in p21 Waf-1, developmentally regulated GTP-binding protein 1 (DRG-1), and E-cadherin in human colon cancer cells." (PMID 23024650, 2012). "Although the basis for these disparate effects has not been established, it appears that activation of PPARγ may have opposing effects on cancer initiation vs progression in colon cancer, similar to our results in lung cancer." (PMID 22145026, 2011). "Treatment of mice lacking one copy of the PPARγ gene with the carcinogen azoxymethane showed a significant increase in the frequency of colon tumors, while other studies with mice having a breast epithelium specific ablation of PPARγ showed no increase in breast tumors." (PMID 21144036, 2010). "Since HT-29 human colon cancer cells are not sensitive to EGF stimulation due to the lack of a canonical peroxisome proliferator-activated receptor-gamma response element (PPRE), we speculated that EGF may regulate caveolin-1 expression through peroxisome proliferator-activated receptor-gamma." (PMID 19816600, 2009). "While the role of miRNAs in suppressing PPARG expression has not been adequately studied in NMSC, one study demonstrated that miR-27b, miR-130b, and miR-138 are all upregulated in colon cancer and correlate negatively with PPARG mRNA and protein expression." (PMID 39195246, 2024). "PPARγ increased in most cancer specimens versus mucosa, with a decrease in c-Myc and in PCNA proteins, suggesting that colon cancer growth is due to increased cell survival rather than increased proliferation." (PMID 17389773, 2007). "Although the mechanism of growth inhibition via the PPARγ-PSF axis in colon cancer cells has not been fully elucidated, our present study demonstrated that the PSF expression level is an important regulatory element for colon cancer cell growth." (PMID 23516550, 2013).
liver fibrosis (172 papers, 2007 to 2026). "Here, we sought to design a macrophage-selective treatment with a low dose of GW1929 PPARγ agonist linked to carbon-based nanoparticles (DGNS-GW) as drug delivery systems for the treatment of liver fibrosis." (PMID 37242695, 2023). "In the current study, we also observed an association between enhancer polymorphism rs10865710 in the PPARG gene and liver fibrosis progression." (PMID 37059745, 2023). "We used a synthesis method modified from a previous design of dendrimer–graphene nanostars (DGNS) to obtain DGNS linked to a low dose of the GW1929 PPARγ agonist (DGNS-GW) to induce macrophage M2 polarization for the treatment of liver fibrosis." (PMID 37242695, 2023). "The H3K9-specific Jumonji demethylase JMJD1A has been reported to bind to the Pparγ promoter, which then decrease the number of H3K9me2 marks in this region, causing modulation of hepatic stellate cells activation and liver fibrosis." (PMID 37190114, 2023). "EZH2 is a histone H3K27 methylation leads to recruitment of the PRC1 Polycomb complex which causes chromatin condensation, and promotes hepatic fibrosis by repressing the transcription of PPARG." (PMID 36612019, 2022). "Studies have shown remarkable liver fibrosis in PPARγ-deficient mice and suppressed HSCs and fibrogenesis following PPARγ overexpression." (PMID 31557909, 2019). "The therapeutic effects of current PPARγ agonists in treating liver fibrosis caused by other types of liver injury are unknown." (PMID 41235615, 2025). "Another anti-fibrotic gene repressed by EZH2 is peroxisome proliferator-activated receptor gamma (PPARγ), a ligand-activated transcription factor that is linked to promoting protective effects against lung, cardiac, kidney, and liver fibrosis." (PMID 37476157, 2023). "Furthermore, capsaicin has been shown to stimulate PPARγ, which causes the suppression of inflammation during liver fibrosis." (PMID 36359200, 2022). "In addition, liver fibrosis is associated with changes in DNA methylation density at the PPARG promoter analyzed in circulating cell-free DNA obtained from patient plasma." (PMID 36612019, 2022). "PPARγ overexpression could directly reverse liver fibrosis in mice fed with a methionine–choline-deficient (MCD) diet by reducing the expression of α-SMA and tissue inhibitors of metalloproteinases (TIMPs) and increasing HSCs cell apoptosis." (PMID 34361064, 2021). "In addition, macrophage-specific Pparγ deficiency showed significantly increased expression of liver fibrosis-related genes, such as transforming growth factor-beta 1 (TGF-β1), actin alpha 2, collagen type I alpha 1 (COL1A1), and tissue inhibitor of metalloproteinase (TIMP)-1, in MASH liver." (PMID 39200340, 2024). "PPARγ is protective against liver fibrosis and metabolic dysfunction; its normalization by NR suggests mitigation of stress-related fibrogenic processes." (PMID 41566055, 2026). "We found that the reduction of adiponectin in LX2 cells dramatically reduced the expression of PPARγ, suggesting the possible involvement of PPARγ in adiponectin-mediated suppression of liver fibrosis." (PMID 39792554, 2025). "Overall, this study showed that FABP7 in hepatic macrophages regulated PPARγ expression and M2 polarization, thereby promoting liver fibrosis via fibroblast activation and CD4+ T-cell migration." (PMID 40017805, 2025). "Research demonstrates curcumin suppresses GLUT2 transcriptional activity via PPARγ activation and promotes de novo glutathione biosynthesis, thereby eliminating HSC activation and ultimately ameliorating hyperglycemia-associated liver fibrosis." (PMID 41357857, 2025). "The adiponectin-PPARγ axis in HSCs constitutes a potential therapeutic target to prevent or reverse liver fibrosis and contain HCC progression in patients." (PMID 39792554, 2025).
liver fibrosis (continued). "The bioinformatics analysis indicated that TNF, IL-6, PPARG and MMP9 were promising candidate genes that can serve as diagnostic and prognostic biomarkers for liver fibrosis." (PMID 39869574, 2025). "Here, we provide evidence demonstrating that HSC-derived adiponectin regulates liver fibrosis via PPARγ, and overexpression of PPARγ can partially recapitulate the phenotypes of adiponectin overexpression in HSCs." (PMID 39792554, 2025). "Based on these observations, we propose that the stellate cell-specific adiponectin-PPARγ axis in HSCs is a crucial regulator of liver fibrosis." (PMID 39792554, 2025). "To further examine the role of HSC PPARγ expression in liver fibrosis, we crossed the Lrat-rtTA line with the TRE-PPARγ2 line to generate LPPARG2 mice." (PMID 39792554, 2025). "The results showed that AcAc was able to significantly down-regulate the expression of fibronectin and α-SMA, while up-regulating the level of PPARγ, suggesting that AcAc inhibited hepatic fibrosis by activating PPARγ." (PMID 40006033, 2025). "Taking advantage of these two as well as other mouse models, we demonstrate a crucial role of local adiponectin production in HSCs in the regulation of liver fibrosis via peroxisome proliferator-activated receptor gamma (PPARγ)." (PMID 39792554, 2025). "Clinical trials have demonstrated the effectiveness of PPARγ agonists in treating MASH-related liver fibrosis." (PMID 41235615, 2025). "Some studies have shown that epigenetic modification of PPARγ is also involved in the regulation of liver fibrosis." (PMID 38931227, 2024). "Similar results were obtained in the case of liver fibrosis, where the inflammatory state and liver fibrosis strongly correlated with the hypermethylation of PPARG, resulting in lower expression." (PMID 39595621, 2024). "ATG can activate AMPK/PPARγ pathway to restore the activated hepatic stellate cell to quiescence thereby improving liver fibrosis." (PMID 39359922, 2024). "Within the realm of PPAR agents, the utilisation of nanomedicine as a carrier for PPARγ agent has been tested for the treatment of chronic liver disease and have shown to reduce liver fibrosis and inflammation." (PMID 38993197, 2024). "The activation of peroxisome proliferator-activated receptor γ (PPARγ) plays an important role in the occurrence and development of liver fibrosis." (PMID 38931227, 2024). "In a mouse model of liver fibrosis, miR-155 is induced, and PPARγ is its direct target in both naive and alcohol-treated macrophages, implying that PPARγ also functions as an antifibrotic gene." (PMID 37190114, 2023). "Studies have shown that inhibition of the STAT6/PPARγ pathway in liver fibrosis can reduce M2 macrophage polarization and delay fibrosis progression." (PMID 37231189, 2023). "Consistently, adenovirus-mediated overexpression of PPARγ or treatment with rosiglitazone, a PPARγ agonist, alleviates inflammatory responses and liver fibrosis in a NASH murine model." (PMID 37760020, 2023). "A histone deacetylase enzyme, Sirtuin 1 (SIRT1), can deacetylate EZH2 to decrease its stability and lead to the de-repression of PPARγ in liver fibrosis." (PMID 37476157, 2023). "The flavonoids enhanced the expression of Stat1, Pparg, Hsp90aa1 genes, signal transduction and transcriptional activator 1 (STAT1), and peroxisome proliferator-activated receptor G (PPARG) proteins, which play key roles in the pathogenesis of liver fibrosis." (PMID 37175164, 2023). "Described as an antifibrotic gene, the hypermethylation of PPARγ has been studied, and it has been confirmed that in mild liver fibrosis, the PPARγ promoter region is hypomethylated compared with severe fibrosis." (PMID 36864460, 2023). "PPARγ agonists are effective against fibrosis across experimental models of liver fibrosis and are currently being used in clinical trials." (PMID 37476157, 2023).